TLR7 (toll like receptor 7)
Diseases named in the same sentence as TLR7 in open-access papers (continued):
Sharing a sentence is not in itself a finding about the gene and the disease.
COVID-19 (continued). "Of note, recent genetic analysis of 4 young brother pairs (range, 21–32 years) with respiratory insufficiency due to severe COVID-19 suggested TLR7 deficiency with reduced production of IFN-γ, a type II IFN as the underlying cause." (PMID 33263173, 2021). "In support of the key role of TLR7 in certain infections, a recent study has identified loss-of-function mutations of TLR7 associated with severe forms of COVID-19 in young men, suggesting a key role of TLR7 in the protective response against SARS-CoV2." (PMID 33498655, 2021). "The rarity of TLR7 deficiency in the general population is consistent with TLR7 deficiency underlying critical COVID-19." (PMID 34413140, 2021). "In July 2020 rare, deleterious germline variants in the X-chromosomal Toll-like receptor 7 (TLR7) gene were reported in young and, otherwise, healthy males with severe COVID-19." (PMID 34367187, 2021). "Consistent with this, familial deficiency in TLR7 leads to increased susceptibility to severe COVID-19." (PMID 34578420, 2021). "In follow-up of the recent discovery of TLR7 deficiency in patients with severe COVID-19, we aimed to prospectively determine the presence of TLR7 variants in young and previously healthy men with severe COVID-19." (PMID 34367187, 2021). "Accordingly, these low effect size genetic variants in TLR7 have been proposed as a possible explanation of the male sex bias in COVID-19 severity because of its localization on the X chromosome and well-established function in innate immunity." (PMID 34367187, 2021). "Second, the TLR7 variant identified in patient 13 segregates in a brother who only experienced mild COVID-19." (PMID 34367187, 2021). "TLR7 deficiency has been reported as a genetic mediator for severe COVID-19 especially in younger males, with percentages of 1-2% found across cohorts." (PMID 34858409, 2021). "The patients’ first-degree family contracted COVID-19 at the time the patient developed symptoms, including his 24-year-old brother, who had only minor symptoms but was shown to be a carrier of the TLR7 variant." (PMID 34367187, 2021). "Recently, loss-of-function variants in TLR7 were identified in two families in which COVID-19 segregates like an X-linked recessive disorder environmentally conditioned by SARS-CoV-2." (PMID 33650967, 2021). "Functional studies have identified rare loss-of-function variants of the X-chromosomal TLR7 in severe COVID-19 patients." (PMID 34440121, 2021). "A plausible mechanism accounting for the severity of COVID-19 in TLR7-deficient patients is the impairment of type I IFN production by pDCs upon stimulation with SARS-CoV-2, which can enter these cells, but cannot replicate productively within them." (PMID 34413140, 2021). "As regards the involvement of DCs in determining SARS-CoV-2 infection susceptibility and COVID-19 severity, experimental data demonstrated that TLR7 plays a critical role through viral single-stranded RNA recognition in the endosomal compartments of pDCs." (PMID 34595175, 2021). "Thirdly, the size of this study does not permit to draw any firm conclusions on the prevalence of loss of function TLR7 variants in males with severe COVID-19." (PMID 34367187, 2021). "Male patients with severe COVID-19, rare putative loss-of-function variants of X-chromosomal TLR7 were identified that were associated with impaired type I and II IFN responses." (PMID 33255528, 2020). "Several studies have suggested that a loss of function in the X-chromosomal TLR7 could be a genetic factor in COVID-19 severity in males." (PMID 40495154, 2025). "TLR7, which encodes a key receptor for single-stranded RNA (ssRNA) virus of the innate immune system, was recently associated with X-linked immunodeficiency and COVID-19 susceptibility." (PMID 40423910, 2025). "Notably, X-linked recessive TLR7 defects were observed in 1% of COVID-19 patients who presented severe COVID-19." (PMID 40162785, 2025).
COVID-19 (continued). "Low TLR7 expression has been described to be associated with COVID-19 severity, and bronchoalveolar lavage fluids from severe and deceased patients have been reported to contain fewer TLR7-expressing cells than mild and samples from survivor patients, respectively." (PMID 41445728, 2025). "Inherited TLR7 or I-IFN deficiency confers a predisposition to life-threatening COVID-19." (PMID 40227192, 2025). "Additionally, we identify associations between several common TLR7 variants and the development of moderate to severe COVID-19 presentations." (PMID 40423910, 2025). "While TLR7 deficiency predisposes to severe COVID-19, enhanced TLR7 responses may confer sterilizing immunity to SARS-CoV-2, with chilblains as a trade-off." (PMID 40227192, 2025). "Ex vivo stimulation of pDCs, DCs, and monocyte–macrophages isolated from the peripheral blood of COVID-19 patients with the TLR7 loss-of-function variant resulted in reduced IFN/ISG levels compared to the cells from control COVID-19 patients (53, –, 55, 80, 81)." (PMID 40162785, 2025). "Likewise, older male patients with X-linked TLR7 deficiency were found to be at greater risk of hypoxemic COVID-19 than younger patients." (PMID 39680367, 2025). "Overall, this is an example of how genetic and acquired factors may increase susceptibility and severity of specific infections, as similarly described for a patient affected by severe COVID-19 with both TLR7 deficiency and anti-IFN autoantibodies." (PMID 38976510, 2025). "TLR7 recognizes single stranded RNA, particularly of viruses, so this finding suggests that viruses known to affect cognitive function (such as COVID-19) could induce neuroinflammation and neuronal loss by these means." (PMID 38550989, 2024). "We first queried for variants that may cause TLR7 deficiency, since at the time of writing, this represents the most robustly established monogenic cause of severe COVID-19, particularly in young men." (PMID 39715278, 2024). "Different TLR7 variant polymorphisms are present in a minority of the total population, and some of these variants have lost their function due to mutations in TLR7; this may drive severe COVID-19 in males because TLR7 is located on the X chromosome." (PMID 39062904, 2024). "Hence, individuals with unique loss-of-function (LoF) variants in TLR7 (rs189681811 and rs147244662) that are associated with COVID-19 severity have been linked with an abrogated production of IFNI and II." (PMID 37112884, 2023). "Loss-of-function (LOF) mutations in TLR7 led to critical COVID-19 in men." (PMID 37567916, 2023). "Several TLRs, such as TLR2, TLR3, TLR4 and TLR7, have been associated with COVID-19 severity." (PMID 37175768, 2023). "Notably, X-linked recessive TLR7 deficiency alone accounts for approximately 1% of critical cases of COVID-19 in male patients under the age of 60 years." (PMID 37047709, 2023). "We investigate the mechanism associated with the severity of COVID-19 in men with TLR7 mutation." (PMID 37567916, 2023). "Men with loss-of-function (LOF) mutations in TLR7 had severe COVID-19." (PMID 37567916, 2023). "The characterization of TLR7 variants in patients with critical COVID-19 could prove important for a possible therapeutic approach." (PMID 37488607, 2023). "This case illustrates a role for TLR7 in long-term COVID-19 complications and highlights that TLR7 deficiency in the future may be addressed as a therapeutic measure." (PMID 38093758, 2023). "Here, we explore the association of TLR7 LOF mutations with the severity of COVID-19." (PMID 37567916, 2023). "TLR2, TLR3, TLR4 and TLR7 have been associated with COVID-19 severity." (PMID 37175768, 2023). "Overall, TLR7 deficiency was found to account for about 1% of cases of critical COVID-19 in men." (PMID 37196358, 2023).
COVID-19 (continued). "Herein, we present the detailed clinical, immunological and genetic characterization of a unique IEI patient with critical COVID-19 pneumonia, who has pathogenic mutations in both X-linked TLR7 and autosomal ATM (reported as P6 in a large COVID-19 cohort, with a TLR7 mutation)." (PMID 34686943, 2022). "Based on these publications van de Veerdonk and Netea (2021) concluded that variants of this single gene TLR7 are responsible for an important proportion of risk factor for severe COVID-19 in men under 50 due to the mutations leading to a loss-of-function in the antiviral response to SARS-CoV-2." (PMID 35065665, 2022). "In addition, missense TLR7 variants in young men with severe COVID-19 were also reported by another group." (PMID 35631059, 2022). "Additionally, 3 of 252 (1.1%) patients with severe COVID-19 defined as hospitalization with low-flow oxygen (<6 l/min) that were also included in the HGE cohort carried deleterious TLR7 variants." (PMID 35986347, 2022). "As TLR7 plays a prominent role in the pathogenesis of DM, we suspect that TLR7 agonists such as those present in RNA/DNA vaccines utilized for COVID-19 may be sufficient to promote inflammatory signals associated with DM." (PMID 36419787, 2022). "Furthermore, loss-of-function variants of X-chromosomal TLR7 have been identified in young male patients with severe COVID-19." (PMID 34991643, 2022). "Indeed, very rare variants in TLR7 have been identified in patients with severe or critical COVID-19 patients." (PMID 34686943, 2022). "Moreover, loss-of-function variants of TLR7 have recently been reported to underlie a strong predisposition to severe COVID-19 in a small number of males." (PMID 35832809, 2022). "TLR7-deficiency as a risk factor for severe COVID-19 has been widely replicated, both by additional case reports and by larger-scale exome association studies and with consistent OR close to 5, overall accounting for over 1% of male individuals with critical COVID-19 pneumonia." (PMID 35768520, 2022). "Further, this our results suggest that TLR7 mediated genetic predisposition to severe COVID-19 may be a dominant or co-dominant trait, an observation that cannot be made in cohorts limited to male participants." (PMID 36327219, 2022). "A loss-of-function mutation in TLR7 increases COVID-19 severity in young males." (PMID 35847031, 2022). "Together, these findings suggest that TLR7/8 signaling may both induce and/or exacerbate the inflammation associated with COVID-19." (PMID 35261923, 2022). "Given that TLR7 is found on the X-chromosome, TLR7 may influence gender-based differences in COVID-19 susceptibility and severity." (PMID 36419185, 2022). "In addition to the rare variants in known IEI that were associated with critical COVID-19, using an unbiased approach, we identified X-linked TLR7 deficiency as the first novel immunodeficiency in patients with critical COVID-19." (PMID 35986347, 2022). "In addition, multiple studies found that the pLoF variants in TLR7 gene enriched in severely affected male patients, and the deficiency of TLR7 would impair innate immunity and increase severity of COVID-19." (PMID 35694544, 2022). "Furthermore, functional TLR7 genetic variants have been linked to COVID-19 severity in multiple studies." (PMID 36419185, 2022). "In addition, single-stranded RNA (ssRNA) is the natural ligand of TLR7, and worldwide pandemic diseases such as flu and COVID-19 are all caused by RNA viruses." (PMID 35069523, 2021). "Later, more such cases of deleterious TLR7 variants in severe male patients have been described, suggesting that a loss-of-function of TLR7 could explain some cases of severe COVID-19 which result in functional defects of type 1 IFN." (PMID 34858409, 2021). "X linked differences in TLR7 expression may not only contribute to COVID-19 susceptibility, but also to hepatitis C virus (HCV) or human immunodeficiency virus (HIV) susceptibility." (PMID 34858409, 2021).
COVID-19 (continued). "For instances, deletion or mutation of TLR7 has been attributed to severity of COVID-19 in young adults, in which protection or early administration of MoAbs (REGN-CoV-2) may limit morbidity and mortality." (PMID 34335596, 2021). "Notably, very rare loss-of-function variants of TLR7 in 2 independent families were associated with severe COVID-19 in males." (PMID 34375313, 2021). "An example arises from a recent preliminary communication, in which a case series study presented that genetic variants leading to TLR7 loss of function were present in 4 young male COVID-19 patients, all previously healthy with unsuspected severe complications of COVID-19 of which 1 patients died." (PMID 33519463, 2020). "Interestingly, a recent case-series has shown that four young males with severe COVID-19 harbored rare TLR7 variants, which hampered interferon responses upon TLR7 engagement." (PMID 33414783, 2020). "Molecular aspects may aid in refining risk assessment in COVID-19, such as suggested in a recent case series of patients who had loss-of-function variants of TLR7, associated with impaired type I and II interferon responses." (PMID 33163005, 2020). "Additionally, given that mice are commonly used animal models for SARS-CoV-2 pathogenesis studies, it is important to define whether TLR7 deficiency in mice replicates the COVID-19 phenotype observed in humans." (PMID 40162785, 2025). "Importantly, this observation was consistent across both sexes, suggesting that TLR7-mediated genetic predisposition to severe COVID-19 may be a dominant or co-dominant trait, an observation that cannot be made in cohorts limited to male participants." (PMID 37175768, 2023). "Conversely, variants of proteins such as TLR7 could lead to severe cases of COVID-19." (PMID 37175995, 2023). "Moreover, it has been proposed that more common, lower effect size TLR7 variants could contribute to the male sex bias that is observed in severe COVID-19, because of its innate immune function and X-chromosomal localization." (PMID 35986347, 2022). "Finally, our genetic score did not include the sex chromosomes: many immune genes are located on the X-chromosomes, and we cannot exclude a sex-biased genetic susceptibility for severe COVID-19 involving such genes, as recently shown for TLR7-deficiency in young men." (PMID 35634344, 2022). "Moreover, authors identified loss-of-function variants of TLR7 in males with diagnosed COVID-19." (PMID 35409036, 2022). "Furthermore, a more recent nested case–control study identified in the TLR7 gene, loss-of-function variants such as p.(Ser301Pro), p.(Arg920Lys) (rs189681811), and p.(Ala1032Thr) (rs147244662) found in 2.1% of young males with severe COVID-19." (PMID 35618891, 2022). "Thus, X-linked TLR7 deficiency represents a novel IEI predisposing to severe COVID-19." (PMID 35748970, 2022). "Furthermore, in pan-ancestry whole-exome sequencing data of over 500,000 individuals from the UK biobank, including more than 20,000 patients who contracted COVID-19, the burden of rare variants in TLR7 was found to be significantly increased in patients with severe COVID-19 (OR 4.53 (2.64–7.77))." (PMID 35986347, 2022). "Therefore, it is probable that any change in TLR7 signaling might increase the risk for a dysregulated immune response seen in severe COVID-19." (PMID 33414783, 2020). "The association between TLR7 and OAS1 expression with COVID-19 severity was especially relevant among the significant results obtained." (PMID 41445728, 2025). "In this context, the following TLRs have been associated with the severity of COVID-19: TLR2, TLR3, TLR4, TLR7, TLR8 and TLR9." (PMID 41011507, 2025). "In conclusion, low TLR7 expression correlates with worse outcome and high viremia in COVID-19 patients." (PMID 41445728, 2025).
COVID-19 (continued). "The results of these genetic factors in the genes (TLR7, UNC13D, DES, SPEG, LZTFL1, ABO, ILRUN, and CACFD1) provide substantial insights into the genesis of cardiovascular issues linked with COVID-19." (PMID 40002898, 2025). "This study highlights the role of TLR7 and OAS1 expression in COVID-19, revealing associations with viral load and severity." (PMID 41445728, 2025). "Regarding the downregulation of TLR7 expression over time, our results suggest that high TLR7 levels protect against severe COVID-19 outcome, and as the disease resolves, TLR7 expression decreases." (PMID 41445728, 2025). "In our previous work, we observed increased frequencies of TLR3, TLR7, and TLR8 variants among severe and critical COVID-19 cases." (PMID 40943412, 2025). "This was characterized by low levels of IRF7, IFNβ1, ISG15 and IFNγ, highlighting the importance of intact TLR7 signaling in the pathogenesis of severe COVID-19." (PMID 41011507, 2025). "As COVID-19 progresses, platelets internalize circulating viral particles and activate TLR7, triggering complement component C3 release, which also promotes neutrophil extracellular trap formation (NETosis)." (PMID 40282925, 2025). "In summary, our study establishes a compelling link between TLR7 LOF variants in men and increased susceptibility to severe COVID-19, exemplified by the N215S variant, which completely abolishes signal transduction upon stimulation." (PMID 40423910, 2025). "COVID-19 serves as another example, where we explored its pathogenesis by leveraging reQTLs generated following the activation of TLR7/8, a pathway relevant to the disease." (PMID 40208878, 2025). "Conversely, stimulating PBMCs from severe COVID-19 patients, characterized by rare loss-of-function (LOF) variants of the TLR7 gene, with the TLR7 agonist imiquimod (IMQ), revealed an impaired IFN-I response." (PMID 41011507, 2025). "It has been reported that among patients with severe COVID-19, some have deficiencies in toll-like receptor 3 (TLR3), TLR7, or interferon (IFN) signaling, or possess autoantibodies against type I IFNs." (PMID 39652608, 2024). "In COVID-19, TLRs, especially TLR7 and TLR8, which bind to single-stranded RNA, are enriched in lung tissues and play critical roles in different stages of the immune response." (PMID 38932146, 2024). "In the intervening decade, several alternative TLR7 agonists have also emerged and advanced into clinical development, such as the alum adsorbed TLR7/8 SMIP present in a widely distributed COVID-19 vaccine." (PMID 38332005, 2024). "Most type I interferon-inducible genes were elevated in similar patterns in both SLE and COVID-19, with the exception of TLR7, which was DE only in SLE." (PMID 38302132, 2024). "In previous studies of familial clusters of patients with severe COVID-19 across Sweden, we identified two brothers with a homozygous LoF IRF7 variant, as well as two brothers with a novel X-linked TLR7 LoF variant." (PMID 38231281, 2024). "The usage of TLR7 agonists to stimulate innate and acquired immunity was effective against COVID-19." (PMID 37567916, 2023). "MERCK KGaA has initiated a randomized double-blind phase II clinical trial with M5049, a selective TLR7/8 pharmacological inhibitor initially designed to treat autoimmunity, for the treatment of severe symptoms of COVID-19." (PMID 36926280, 2023). "Increased NF-κB activity was induced in TLR7/8-expressing cells stimulated with COVID-19 patient–derived EVs, compared to those treated with HC subject–derived EVs (P < 0.005)." (PMID 37904132, 2023). "TLR7 agonists induce the Th1 antiviral response and are effective as vaccine adjuvants against COVID-19." (PMID 37567916, 2023). "Overall, COVID-19 severity appears to be similar in patients with MyD88/IRAK-4 deficiency and in those with TLR7 deficiency." (PMID 36880831, 2023).